ATG7 (autophagy related 7)
Diseases named in the same sentence as ATG7 in open-access papers (continued):
Sharing a sentence is not in itself a finding about the gene and the disease.
glioma (21 papers, 2012 to 2025). A benign or malignant brain and spinal cord tumor that arises from glial cells (astrocytes, oligodendrocytes, ependymal cells). "Therefore, C6 glioma cell migration capability was used as a biological functional readout to monitor the impact of Atg7 deficiency on the response of BV2 microglia to a stimulus promoting an immunosuppressive and tumor-supportive phenotype." (PMID 34082793, 2021). "In addition, we used a shRNA against ATG7 to generate an autophagy deficient mouse glioma cell." (PMID 40964044, 2025). "Using siRNAs against autophagy-related genes ATG7, ATG4b, we assessed the viability of both mouse and human glioma cells treated with radiation." (PMID 40964044, 2025). "To this end, we used siRNAs targeting ATG4b and ATG7 and assessed the viability of mIDH1 glioma NS treated in combination with radiation." (PMID 40964044, 2025). "Inhibiting autophagy in vivo by administration of synthetic protein nanoparticles encapsulating siRNA targeting Atg7 sensitized mIDH1 glioma cells to radiation, resulting in tumor regression, long-term survival, and immunological memory." (PMID 40964044, 2025). "Using our cell implantable mIDH1 glioma model, we evaluated the therapeutic impact of autophagy inhibition using SPNPs loaded with siRNA targeting ATG7 (ATG7i-SPNP) in combination with IR." (PMID 40964044, 2025). "The glycoside flavonoid purple sweet potato delphinidin-3-rutin (PSPD3R) suppressed in vitro and in vivo glioma proliferation regulating autophagy by inducing the AKT/cAMP response element-binding protein (CREB)/miR-20b-5p/autophagy related 7 (Atg7) pathway." (PMID 38201989, 2024). "MiR-186 can decrease Atg7 and Beclin1 expression levels, thereby inhibiting autophagy in glioma-conditioned human cerebral microvascular endothelial cells." (PMID 38553562, 2024). "It was explained that knockdown of ATG7 and Beclin 1, which are essential autophagy genes, sensitized the glioma cells in vitro." (PMID 33525678, 2021). "In the current study, knocking-down Atg7 significantly enhanced the ibrutinib-induced apoptosis of glioma cells in vitro." (PMID 28716053, 2017). "In addition, we evaluated the impact of the molecular inhibition of autophagy on glioma cells’ radio-responses through siRNAs against autophagy-related genes ATG7 and ATG4b and through the knockdown of ATG7 in mouse glioma cells." (PMID 40964044, 2025). "In addition, we observed very little differences of Atg7 levels in C6-glioma cells, and there was a decrease in N2a cells after Cur and or SLCP treatment." (PMID 30669284, 2019). "EMAP-II induced the autophagy of human U-87 and U-251 glioma cells, which might be correlated with the up-regulation of ATG7 and ATG5." (PMID 27242439, 2016). "Therefore, EMAP-II may up-regulate expression of ATG5 and ATG7 via down-regulation of miR-20a, inducing autophagy in glioma cells." (PMID 27242439, 2016). "To ensure that ATG7 was suppressed in vivo in response to ATG7i-SPNP treatment, we performed immunohistochemistry on mIDH1 glioma bearing mice treated with ATG7i-SPNP." (PMID 40964044, 2025). "The knockdowns of ATG7 and autophagy inhibitor Baf A1 are able to abrogate AMF-inducing ferroptosis and autophagic cell death in glioma cells." (PMID 35002708, 2021). "We observed that the selective knockdown of ULK1, Atg5, or Atg7 or pharmacological inhibition of autophagy with 3MA increased the levels of active caspase 3, 7 and PARP degradation in WIN55,212-2-treated LN18 glioma cells." (PMID 33499365, 2021). "AMF increases the autophagic flux of glioma U251 and U373 cells via up-regulating the autophagy-relevant proteins, such as Beclin1, LC3B, ATG5, ATG7 and the phosphorylation of AMPK or suppressing the phosphorylation of mTOR and p70S6K." (PMID 35002708, 2021). "We have investigated different autophagy markers, such as Atg5, Atg7, Beclin-1, LC3A/B, and p62, from all three GBM cell lines (U-87MG, GL261, and F98), and from C6-glioma and N2a cells." (PMID 30669284, 2019).
glioma (continued). "EMAP-II upregulated ATG7 and ATG5 to enhance U87 and U251 glioma cell autophagy via miR20a down-regulation." (PMID 29632473, 2018). "EMAP-II up-regulated the expression of the proteins LC3-II/I, ATG7 and ATG5, but down-regulated P62/SQSTM1 expression in the U-87 and U-251 glioma cells, demonstrating that the antitumor activity results from the induction of autophagy, not apoptosis." (PMID 27242439, 2016). "We found that mIDH1 glioma-bearing mice treated with ATG7i-SPNPs exhibited no ATG7 expression when compared to saline-treated mIDH1 glioma bearing mice." (PMID 40964044, 2025). "As expected, overexpression of ASCL2 caused increased autophagic flux, as evidenced by conversion from LC3‐I to LC3‐II and degradation of SQSTM1 in multiple glioma cells, but did not significantly affect ATG7 and BECN1." (PMID 35882624, 2022). "Moreover, the viability of glioma cells is partly under the control of miR-20a97, while purple sweet potato delphinidin-3-rutin regulates the regulatory function of miR-20b-5p through the protein kinase B (AKT)/Creb/miR-20b-5p/Atg7 pathway." (PMID 38553562, 2024). "Western blot analysis showed that knock down of lncRNA DLEU1 dramatically reduced the LC3II expression, transition from LC3I to LC3II, as well as the expression of p62 and ATG7, which suggested that lncRNA DLEU1 deletion could suppress autophagy in glioma cells." (PMID 33362537, 2020). "Furthermore, when we treated two different mIDH1 mouse glioma cell models with α-ketoglutarate (α-KG), we found that the mIDH1 cells reverted the expression patterns showing significant reduction in several key autophagy regulators including pATG4b, UVRAG, ATG7, and ATG9b." (PMID 40964044, 2025).
prostate carcinoma (21 papers, 2014 to 2025). A carcinoma that arises from epithelial cells of the prostate gland. "Furthermore, it was reported that autophagy is essential for the development of prostate cancer in a mouse model with inducible prostate-specific deficiency in the Pten tumor suppressor and autophagy-related-7 (Atg7) genes." (PMID 34298710, 2021). "Here, we showed that ATG5 and ATG7 are required for androgen-induced LDs in prostate cancer cells as KD of ATG5 and ATG7 prevented the formation LDs." (PMID 37874216, 2023). "MIR493 upregulates PHLPP2 (PH domain and leucine rich repeat protein phosphatase 2) to promote expression of BECN1 and ATG7, resulting in autophagy and reduced ability of prostate cancer cells in colony formation." (PMID 35317831, 2022). "Further inhibition of ATG7 also enhances the efficacy of mitoxantrone in prostate cancer apoptosis, demonstrating a protective role of autophagy in prostate cancer and its inhibition by this oncolytic virus." (PMID 35317831, 2022). "The stimulated autophagy flux, and up-regulated expression of the autophagy-specific genes, ATG5 and ATG7 observed in some human prostate cancer cells." (PMID 29606130, 2018). "For example, miR-96 can promote or inhibit autophagy by principally inhibiting mTOR or ATG7 depending on the expression levels of miR-96 in prostate cancer cells under hypoxia." (PMID 27803889, 2016). "Induction of autophagy-related genes ATG5 and ATG7 was observed at early time points after celastrol treatment in LNCaP prostate cancer cells." (PMID 26473737, 2015). "It should also be noted that prostate cancer has not been associated with alterations in ATG7 expression or function." (PMID 38910881, 2024). "Reciprocally, it has been reported that components of the autophagy machinery (MAP1-LC3, ATG5, ATG7) are required for LD biogenesis; MAPLC31 in prostate cancer cells and hepatocytes, ATG5 in mouse embryonic fibroblasts, ATG5 and 7 in adipocytes." (PMID 37874216, 2023). "Moreover, a recent study showed that knockout of ATG7 (a key autophagic regulator) inhibited prostate cancer progression in castrate-resistant or castrate-sensitive prostate cancer, suggesting that dysfunctional autophagy may also be associated with prostate cancer progression." (PMID 34760337, 2021). "Knockdown of proteasomal catalytic subunits in human prostate cancer cells and immortalized mouse embryonic fibroblasts promoted autophagy activation and upregulated expression of ATG5 and ATG7." (PMID 34222330, 2021). "FOXM1 expression was upregulated in the docetaxel resistant prostate cancer cell lines, downregulation of ATG7, Beclin 1, or cotreatment with chloroquine partly restored sensitivity to docetaxel in the FOXM1-overexpressing prostate cancer cells." (PMID 32587255, 2020). "In this study, we have investigated the function of miR-96 in the regulation of autophagy in prostate cancer cells under hypoxia, and found that miR-96 regulates autophagy under hypoxia via targeting MTOR and ATG7." (PMID 25333253, 2014). "We found that the miR-96 level was reversely correlated with the protein levels of ATG7 and MTOR (p < 0.05), which indicate that miR-96 regulates ATG7 and MTOR in prostate cancer tissues." (PMID 25333253, 2014). "To further investigate the relationship between miR-96 and ATG7 or MTOR, we detected miR-96 expression level, ATG7 and MTOR protein levels in 10 prostate cancer tissues." (PMID 25333253, 2014).
prostate carcinoma (continued). "However, we can't ascertain with confidence that targeting ATG7 is an off-target effect, because miR-96 level was inversely correlated with the protein levels of ATG7 in prostate cancer tissues, which indicated miR-96 might target ATG7 in prostate cancer tissues." (PMID 25333253, 2014). "Although it has been reported previously that autophagy might be induced upon treatment with BTZ or MZB, as demonstrated by increased expression of LC3 II, ATG5, and ATG7 in human prostate cancer cells, it has not yet been confirmed in other studies." (PMID 39204194, 2024). "Finally, proteasome inhibition with bortezomib in human prostate cancer cells, and immortalized mouse embryonic fibroblasts promoted autophagy activation and upregulated expression of ATG5 and ATG7, which depended on phosphorylation of eIF2α, a downstream element of the PERK arm of the UPR." (PMID 34222330, 2021). "MIR34A-loaded chitosan nanoparticles stimulate autophagy in prostate cancer cells independent of BECN1, ATG4, ATG5 and ATG7, known as non-canonical autophagy." (PMID 35317831, 2022).
colon carcinoma (20 papers, 2013 to 2025). "In contrast, other literature proposes that acetylated, rather than phosphorylated, FOXO1 plays a key role in autophagy regulation by interacting with ATG7 in the HCT116 colon cancer cell line." (PMID 41013182, 2025). "Previous reports suggest that the combination of BCG-CWS and IR induces the autophagy of colon cancer cells; moreover, this effect is reduced in colon cancer cells with a knockdown of Beclin 1 or Atg7." (PMID 33302414, 2020). "For example, the pharmacological inhibition of autophagy and the knockdown of Atg-5 or Atg-7 in human colon cancer cell lines have been shown to increase proteasomal activity." (PMID 32784405, 2020). "A pro-death stimulus was also described in 5-FU-induced colon cancer cells, where inhibition of autophagy by Atg7 siRNA or 3-MA augmented apoptosis." (PMID 27506940, 2016). "Our previous studies showed that inhibition of autophagy by 3-methyladenine (3-MA) or small interference RNA targeting Atg7 (Atg7 siRNA) augmented the efficiency of 5-FU by enhancing apoptosis in human colon cancer." (PMID 25526515, 2014). "Knockdown of Atg5 or Atg7 significantly reduced the cytotoxic effect of FK-16, suggesting that FK-16 induced autophagic cell death in colon cancer cells." (PMID 23700428, 2013). "Reciprocally, abolition of AIF/EndoG-dependent apoptosis by AIF- or EndoG-siRNA enhanced Atg5 and Atg7 expression induced by FK-16, indicating that inhibition of AIF/EndoG-dependent apoptosis magnified the autophagic signal in FK-16-treated colon cancer cells." (PMID 23700428, 2013). "The functions of lncRNA AWPPH in proliferation of colon cancer cells were regulated by targeting GLUT-1; LncRNA CCAT1 promotes autophagy of liver cancer cells via regulating ATG7 by sponging miR-181; LncRNA HOTAIR promotes colon cancer progress by targeting miR-34a." (PMID 31900207, 2020). "The result showed that the Livin-H2A.XY142ph axis could directly target ATG5 and ATG7 in colon cancer cells under starvation, while Livin-H2A.XY142F axis had no combination with ATG5/ATG7 in colon cancer cells under starvation." (PMID 31799193, 2019). "However, BIX01294 induced changes could be cell-type specific, as in human colon cancer HCT116 cells the expression of LC3B, ATG9A, ATG4A, but not ATG4B/C, ATG7, BECN1, WIPI1 was increased after BIX01294 treatment." (PMID 27934912, 2016).
leukemia (20 papers, 2015 to 2025). A malignant (clonal) hematologic disorder, involving hematopoietic stem cells and characterized by the presence of primitive or atypical myeloid or lymphoid cells in the bone marrow and the blood. "It was shown that loss of the core autophagy genes ATG5 and ATG7 induced apoptosis and decreased leukemia progression in a murine leukemia model." (PMID 34885250, 2021). "It has been reported that ATG7 deletion caused elevated ROS levels and mitochondrial activity in leukemia cells." (PMID 34885250, 2021). "Furthermore, this study showed that heterozygous loss of Atg5 or Atg7 in a MLL-ENL AML mouse model led to more aggressive leukemia progression, suggesting a tumor-suppressive role for autophagy." (PMID 30678185, 2019). "Mutations in ATGs, such as ATG2B, ATG5, ATG7, ATG9B, and ATG12, have been linked to frameshift mutations in leukemias but also gastrointestinal and liver cancers, highlighting their significance in cancer biology." (PMID 40227235, 2025). "In the mixed lineage leukemia–eleven nineteen leukemia-induced AML model, the role of autophagy in leukemia-initiating cells (LICs) was analyzed by the loss of Atg5 or Atg7." (PMID 39596291, 2024). "In contrast, genetic inhibition of murine Atg5 and Atg7 can prolong leukemia survival and delay the elimination of leukemia-initiating cells." (PMID 37180758, 2023). "Functionally, cytoplasmic TP53INP2 enhanced autophagy activity by promoting the interaction of microtubule-associated protein 1 light chain 3 (LC3) - autophagy-related 7 (ATG7) and further facilitated the survival of leukemia cells." (PMID 36675134, 2023). "Atg7 inhibition is associated with decreased leukemia-initiating cells and prolonged survival of immunodeficient mice with disseminated AML, suggesting a therapeutic role for ATG7 inhibition in AML." (PMID 35526025, 2022). "Conversely, another study on MLL-ENL leukemic mice showed that homozygous deletion of Atg5 or Atg7 in bone marrow cells reduced the frequency of leukemia-initiating cells (LICs) and decelerated leukemia progression." (PMID 34462526, 2021). "In a MLL-ENL mouse model, inhibition of autophagy via knockout of Atg7 resulted in a modest increase of leukaemia survival free of mice together with a decrease in leukaemia initiating cells (LICs)." (PMID 30704144, 2019). "Silencing of the autophagy gene designated Atg7 results in the photosensitization of mouse leukemia L1210 cells to photodynamic effects." (PMID 28839163, 2017). "Flow cytometric analysis of mitochondrial mass also confirmed an inducible mitophagy in Atg7-deleted K562 leukemia cells." (PMID 27091640, 2016). "The Atg7−/− leukemia cells showed a progressive reduction in cell counts in the culture, and the overall growth curve displayed lower proliferation compared with that of Atg7 wild-type controls." (PMID 27091640, 2016). "As the upregulation of the alternative autophagy-essential protein RAB9A was associated with Atg7 deletion in K562 cells, we silenced Rab9A with RNA interference to analyze the importance of the RAB9A protein in alternative mitophagy in leukemia cells." (PMID 27091640, 2016). "Selective induction of mitophagy was associated with the upregulation and localization of RAB9A on the mitochondrial membrane in both wild-type and Atg7−/− leukemia cells." (PMID 27091640, 2016). "For instance, mice lacking functional autophagy genes, including FIP200, Atg7, and Atg12, experience a severe loss of hematopoietic stem cells (HSCs), leading to conditions like anemia and leukemia." (PMID 40066097, 2025). "In addition, inhibition of autophagy, followed by deletion of ATG5 or ATG7, reduces leukemia-initiating cells (LICs) and increases mitochondrial ROS." (PMID 40066097, 2025). "Importantly, autophagy-related proteins (ATG) including ATG5 and ATG7, which are well known critical autophagy genes, have been reported to promote cell proliferation in leukemia." (PMID 34885250, 2021).
leukemia (continued). "In leukemia cells autophagy inhibition by ATG7 depletion resulted in a switch from glycolysis to OXPHOS to either compensate for the reduction in energy levels generated by glucose metabolism, or the elevated ATP production by increased OXPHOS impaired glycolysis." (PMID 34885250, 2021). "To further examine whether Beclin 1 regulates DNA DSB repair in an autophagy-dependent manner, we examined the effect of Beclin 1 on DNA DSB repair in cells that lack ATG7-dependent autophagy using Atg7-knockout K562 leukemia cells." (PMID 28345663, 2017). "After an 18-h treatment with CCCP, mitochondrial mass declined in both wild-type and Atg7−/− leukemia cells, and this degradation could be blocked by 10 nM bafilomycin A1 (Baf-A1), a lysosomal inhibitor." (PMID 27091640, 2016). "Even when ATG7-dependent canonical autophagy is dysfunctional, alternative mitophagy is still able to effectively remove damaged or excessive mitochondria to limit ROS production, DNA damage and apoptotic cell death in the leukemia cells." (PMID 27091640, 2016). "Therefore, we exposed wild-type and Atg7−/− K562 leukemia cells to 3 Gy of nuclear radiation and observed the reduction of TOMM20 in both cell types in response to irradiation." (PMID 27091640, 2016). "In addition, Atg7 deletion markedly decreased leukemic cells in the peripheral blood, a phenomenon attributed to increased apoptosis, suggesting a higher dependency on autophagy compared to bone marrow leukemia cells." (PMID 34445246, 2021). "Members within this cascade such as ATG4B, ATG7, and ATG5 not only show dysregulation in leukemia, but can also be effectively targeted to halt the autophagy process, thus, making interruption of autophagosome maturation an attractive area of study." (PMID 30678185, 2019). "Unexpectedly, the results show that Atg7 deletion did not alter mitochondrial mass or ROS levels in K562 leukemia cells, suggesting that canonical autophagy-defective leukemia cells possibly retained an ability to controlling cellular ROS levels." (PMID 27091640, 2016). "As our previous studies suggested that accumulated pre-leukemic Atg7-deficient cells did not harbor typical AML deletions or translocations and were not transplantable, we next asked whether autophagy has an impact on tumor growth in a mouse leukemia model with an existing translocation." (PMID 26568842, 2015).